SHMT2 (serine hydroxymethyltransferase 2)
Diseases named in the same sentence as SHMT2 in open-access papers (continued):
Sharing a sentence is not in itself a finding about the gene and the disease.
breast carcinoma (continued). "Moreover, patients with breast cancer exhibited higher ISR after chemotherapy, and the elevated mRNA levels of HMOX1, SHMT2 and EIF2A were correlated with poor prognosis." (PMID 31211507, 2019). "Transcript levels of five of the seven metabolic genes (TALDO1, GPI, SHMT2, LDHA, and ADK: 5-gene metabolic signature) and six oncogenes: TAGLN2, NOLC1, HSP90AB1, HDGF, MCM5, and NCL, were elevated in TNBC patients when compared to patients with ER+ breast cancer." (PMID 34711841, 2021). "Furthermore, univariate and multivariate analysis of individual protein expression profiles demonstrated the central role of serine hydroxymethyltransferase 2 (SHMT2) and amino acid transporter ASCT2 (SLC1A5) as independent prognostic factors in breast cancer patients." (PMID 29020998, 2017). "Furthermore, the study of breast cancer patients showed that SHMT2 was highly expressed in breast cancer cells, but not in their normal counterparts and the expression level of SHMT2 was positively correlated with breast cancer grade." (PMID 28177894, 2017). "In 9 out of 17 breast cancer datasets high expression of SHMT-2 predicted negative prognosis." (PMID 25436979, 2014). "Notably, it has been reported that SHMT2 expression, and the one carbon metabolism pathway, is essential for metastasis in TNBC breast cancer models and correlates with poor clinical outcome in patients; however, the mechanisms by which this pathway promotes metastasis remain unclear." (PMID 34638293, 2021). "Although high SHMT2, but not SHMT1, was correlated with breast cancer patient mortality, we found that stromal SHMT1 negativity was associated with poor prognosis." (PMID 24979213, 2014). "The detailed effects of ERRα on SHMT2 expression, on the cell viability, migration capacity, the production of ROS, and the ratio of GSH/GSSG within breast cancer cells with or without resistance to lapatinib could be examined." (PMID 31894856, 2020). "Four breast cancer datasets shared both enzymes, PHGDH and SHMT2, as negative prognostic factors." (PMID 30857125, 2019).
colorectal cancer (27 papers, 2018 to 2025). A primary or metastatic malignant neoplasm that affects the colon or rectum. "However, co-culturing CD8+ T cells with Psat1- or Shmt2-deficient colorectal cancer cells showed enhanced cytotoxic activity, as indicated by increased Granzyme B levels detected via flow cytometry." (PMID 40475762, 2025). "In addition, loss of SHMT2 could mediate 5-fluorouracil chemoresistance in colorectal cancer via promoting autophagy." (PMID 36213384, 2022). "Accumulative evidence revealed that SHMT2 was involved in cancer initiation and development in several types of carcinomas such as glioma, intrahepatic cholangiocarcinoma and colorectal cancer." (PMID 40432803, 2025). "There are studies reporting that succinylation of SHMT2 at the K280 site inhibits the growth of colorectal cancer cells." (PMID 41347062, 2025). "Small interfering RNAs (siRNAs) were used to individually knock down Psat1 and Shmt2 in two murine colorectal cancer cell lines (CT26 and MC38), with knockdown efficiency confirmed by RT-qPCR and Western blot." (PMID 40475762, 2025). "For example, SHMT2 inhibition reduced cell proliferation and tumorigenicity in liver cancer, and the expression of SHMT2 was up-regulated in colorectal cancer cells." (PMID 39189649, 2024). "We found that SIRT3 and SHMT2 were expressed simultaneously in colorectal cancer patients and that the acetylation of SHMT2 K95 was downregulated." (PMID 36684675, 2023). "It has been found in recent studies that the SIRT3 deacetylation of SHMT2 can promote the occurrence of colorectal cancer." (PMID 36684675, 2023). "SHMT2 is significantly upregulated in various cancers, including colorectal cancer, glioma, renal cancer, and bladder cancer." (PMID 37108312, 2023). "It was reported that SHMT2 knockdown inhibited the proliferation and metastasis of colorectal cancer both in vitro and in vivo." (PMID 36077112, 2022). "Knockdown experiments of SHMT2 in colorectal cancer xenografts show total blockage of tumor development only when SHMT1 is also downregulated." (PMID 35831624, 2022). "Previous studies found SHMT2 to be overexpressed in various cancers, including B-cell lymphoma, thyroid cancer, and colorectal cancer, and it played an oncogenic role in these cancers." (PMID 36077112, 2022). "Yet, the function of SHMT2 in tumorigenesis, especially in human colorectal cancer (CRC) progression, remains largely unclear." (PMID 35211429, 2022). "Herein, we detected the expression of SHMT2 protein in colorectal cancer tissues and compared it with the corresponding normal tissues to analyze its relationship with the clinicopathological characteristics and prognosis of colorectal cancer." (PMID 35211429, 2022). "Upregulation of SHMT2, MTHFD2, and ALDH1L2 (10-formyltetrahydrofolate dehydrogenase) were found to be associated with poor survival in colorectal cancer." (PMID 35831624, 2022). "For a comprehensive understanding of the role of SHMT2 in colorectal cancer, we analyzed the gene expression profile of SHMT2-knockdown SW480 and SW620 cells using an Agilent RNA-seq." (PMID 35211429, 2022). "Emerging evidence supports the notion that SHMT2 is a key factor that controls colorectal cancer cell growth, and SHMT2 knockdown impaired the proliferation of colorectal cancer in vitro and in vivo." (PMID 35333683, 2022). "Acetylated SHMT2 exhibits deficient enzymatic activity, which inhibits carcinogenesis, while SIRT3 activates SHMT2 to promote colorectal cancer cell proliferation." (PMID 32724473, 2020). "Our study shows that K95-acetylation of SHMT2 inhibits its function in converting serine to glycine, which results in impaired serine consumption in colorectal cancer cells and inhibits cell proliferation and tumor growth." (PMID 30367038, 2018). "Our results, therefore, provide further rationale for the development of SIRT3/SHMT2 antagonists for colorectal cancer therapy." (PMID 30367038, 2018).
colorectal cancer (continued). "Low glucose increases SHMT2 protein levels by stimulating SIRT3-dependent deacetylation in colorectal cancer cells." (PMID 30367038, 2018). "This indicates an opportunity to develop a drug that targets SHMT2 K95 acetylation or activity for colorectal cancer treatment." (PMID 30367038, 2018). "We found that the loss of SHMT2 results in a similar phenotype as the re-expression of K95Q which significantly decreased NADPH and increased ROS in colorectal cancer cells." (PMID 30367038, 2018). "In our study, we determined that SIRT3 plays an oncogenic role in colorectal cancer via the deacetylation of SHMT2, which results in increased SHMT2 protein and elevated serine consumption in tumor cells." (PMID 30367038, 2018). "A recent study showed that SHMT2 played a crucial role in carcinogenesis and cancer development within several types of carcinoma, such as glioma, intrahepatic cholangiocarcinoma and colorectal cancer." (PMID 40432803, 2025). "The mechanism of SHMT2 in colorectal cancer cell lines was also discussed." (PMID 35211429, 2022). "Compared with matched normal tissues, SHMT2 expression is upregulated in colorectal cancer tissues." (PMID 35211429, 2022). "Low expression of SHMT2 enhances sensitivity to 5-fluorouracil in colorectal cancer." (PMID 36213384, 2022). "Interestingly, a report also showed that SHMT2 drove the progression of colorectal cancer by inhibiting the degradation of β-catenin to promote Wnt/β-catenin signaling in a non-metabolic manner." (PMID 36077112, 2022). "In this study, we observed that SHMT2 is acetylated at K95 in colorectal cancer (CRC) cells." (PMID 30367038, 2018). "Moreover, our clinical analysis showed that high expression levels of SIRT3 in colorectal cancer patients were correlated with a shorter survival time, which is partially due to deacetylated SHMT2 and activated serine consumption in colorectal cancer cells." (PMID 30367038, 2018). "Notably, SHMT2 could drive the progression and metastasis of colorectal cancer via suppressing β-catenin degradation." (PMID 36213384, 2022). "Through the action of serine hydroxymethyltransferase 2 (SHMT2) at the Lys95 site, SIRT3 deacetylates serine and glycine and prevents its lysosomal-dependent degradation, hence accelerating the development of colorectal cancer." (PMID 39479446, 2024). "Here the authors show that acetylation of the lysine-95 (K95) residue negatively regulates SHMT2 expression and activity and is deacetylated by SIRT3 in colorectal cancer." (PMID 30367038, 2018). "We also determined that acetylated SHMT2 leads to the prevention of serine consumption, the upregulation of the serine/glycine ratio and the inhibition of NADPH production, which inhibits colorectal cancer cell growth and tumorigenesis." (PMID 30367038, 2018). "In 5-FU-resistant colorectal cancer (CRC) cells, serine hydroxymethyltransferase-2 (SHMT2), an enzyme involved in mitochondrial serine metabolism, is significantly upregulated, leading to the production of large amounts of one-carbon units, particularly purines." (PMID 40078288, 2025). "SHMT2 can participate in the interaction between transcription factor TCF4 and β-catenin, enhancing its own expression and promoting the growth and metastasis of colorectal cancer cells." (PMID 38594513, 2024). "Similarly, the deacetylation and activation of serine hydroxymethyltransferase 2 (SHMT2) by SIRT3 enhances the conversion of serine to glycine, promoting colorectal cancer cell proliferation by increasing serine consumption and NADPH levels." (PMID 38773972, 2024). "However, the nonmetabolic function of SHMT2 in tumorigenesis, especially in human colorectal cancer (CRC) progression, remains largely unclear." (PMID 33456583, 2021). "SHMT2 may be an oncogene, the succinylation of SHMT2 at K280 sites inhibits colorectal cancer cell growth; however, so far, no relevant literature on the association of SHMT2 with BLCA has been reported." (PMID 34149818, 2021).
colorectal cancer (continued). "Thus, SHMT2 K95 acetylation, SHMT2 protein and SIRT3 may be potential biomarkers for colorectal cancer." (PMID 30367038, 2018).
glioma (23 papers, 2016 to 2025). A benign or malignant brain and spinal cord tumor that arises from glial cells (astrocytes, oligodendrocytes, ependymal cells). "SHMT2 mRNA and protein are strongly expressed in colorectal cancer and gliomas and are associated with poor prognosis." (PMID 38188143, 2024). "Although Gly accumulation caused by SHMT2 was detrimental to cell growth, glioma cells expressed high levels of Gly decarboxylase (GLDC) to decompose Gly into innocuous metabolites, inhibition of which led to the loaded cytotoxic aminoacetone and methylglyoxal." (PMID 34211978, 2021). "According to the molecular mechanism, HOTAIRM1 may improve PTBP1 and IGF2BP2's association, entice them to bind to SHMT2 mRNA, and then boost the quantity of SHMT2 protein by improving the stability of its mRNA, resulting in mitochondrial activity and the malignant growth of glioma." (PMID 40919129, 2025). "It has already been shown that serine hydroxymethyltransferase 2 (SHMT2) was highly expressed in glioma cells surrounding the necrosis zone and hypoxia drives the expression of the key enzymes of serine metabolism in glioma." (PMID 39187509, 2024). "Several studies have demonstrated an association between SHMT2 expression and tumor aggressiveness, suggesting that SHMT2 is an independent predictor of prognosis in glioma, breast and lung cancer." (PMID 35018218, 2022). "Study in gliomas found that SHMT2 contributes to cancer cell survival in the harsh tumor microenvironment, which relies on glycine clearance." (PMID 33863325, 2021). "In gliomas, overexpression of SHMT2 was found to enhance the proliferation and invasion of tumor cells." (PMID 33863325, 2021). "In line with that, clinical detection of SHMT2 expression by immunohistochemistry revealed that it was highly upregulated in glioma tissues compared to that in the control group." (PMID 34476002, 2021). "When Ser was sufficient, PKM2 was stimulated to promote glycolysis of glioma cells, while SHMT2 was activated to counteract augmented TCA cycle activity and save oxygen." (PMID 34211978, 2021). "In glioma cells, SHMT2 has been shown to contribute to cell proliferation in ischemic and hypoxia tumor microenvironments." (PMID 33863325, 2021). "Hypoxia-induced expression of phosphoglycerate dehydrogenase (PHGDH) and the mitochondrial serine hydroxymethyltransferase (SHMT2) was observed in three of five tested glioma cell lines." (PMID 32203214, 2020). "In glioma cells, SHMT2 is responsible for the Warburg effect by limiting the activity of PKM2, thus conferring an advantage to these cancer cells in a poorly vascularized environment." (PMID 31500219, 2019). "Some cancer types, however, show a considerable increase in SHMT2 expression when compared to their healthy counterparts, including breast, glioma, head and neck, lung, stomach, testicular, and thyroid cancer." (PMID 26942765, 2016). "Specifically, SHMT2 is required for glioma cell survival and promotes changes in metabolism that allow tumor cells to adapt to the environment; thus, preventing endogenous glycine production via SHMT2 inhibition is desired as an efficient therapy for tumorigenesis." (PMID 40171278, 2025). "SHMT2 catalyzes the conversion of serine to glycine and one-carbon transfer reactions in mitochondria, plays a key role in the survival of brain cancer cells within the ischemic zones of gliomas." (PMID 36838582, 2023). "SHMT2 expression is an independent predictor of prognosis in glioma, breast and lung cancer." (PMID 35018218, 2022). "Additionally, SHMT2 can drive glioma cell survival in ischemia, which showed that during the process of cancer cell adaptation to the tumor environment, SHMT2 is required." (PMID 34149818, 2021). "Thus far, high expression levels of SHMT2 have been discovered in glioma and hepatocellular carcinoma." (PMID 33163414, 2020).
glioma (continued). "Furthermore, it has been reported that SHMT2 is highly expressed in glioma, intrahepatic cholangiocarcinoma, and hepatocellular carcinoma, reflecting that SHMT2 is partly involved in the process of tumorigenicity." (PMID 33163414, 2020). "In glioma patients, SHMT2 had increased, and its expression was an independent prognostic factor." (PMID 30228815, 2018). "In a previous paper, SHMT2 was shown to be highly expressed in the hypoxic area of GBM and provide a survival advantage to glioma cells adapting to an ischemic microenvironment." (PMID 33468252, 2021). "Additionally, SHMT2 suppresses pyruvate kinase activity, thereby reducing carbon entry into the TCA cycle, a mechanism that enhances glioma cell survival under hypoxic conditions." (PMID 41154660, 2025).
lung carcinoma (22 papers, 2014 to 2025). "Moreover, SHMT2 was significantly upregulated in lung adenocarcinoma tissues, and associated with advanced stages of lung cancer, suggesting its involvement in tumour aggressiveness and potential as a prognostic marker." (PMID 41154605, 2025). "Moreover, increased levels of MCM7 or SHMT2 expression have been associated with poor prognosis in various cancers, including breast and lung cancers." (PMID 39435287, 2024). "SHMT2 is frequently overexpressed in various malignancies, including lung cancer, where its upregulation correlates with poor prognosis and increased tumor aggressiveness." (PMID 40770176, 2025). "Initially, we aimed to assess the relevance of SHMT2 as a potential therapeutic target in lung cancer by evaluating its expression levels in healthy individuals and patients diagnosed with lung adenocarcinoma (LUAD)." (PMID 40770176, 2025). "While both SHMT1 and SHMT2 are overexpressed in lung cancer tissues, their utility as independent prognostic markers remains uncertain, which warrants further validation in a larger cohort." (PMID 41154605, 2025). "In the present study, we found that SHMT2 knockdown also inhibited the EMT in lung cancer cell lines and had a notable influence on cell migration, indicating that SHMT2 is a tumor promoter." (PMID 38577602, 2024). "Although SHMT2 is the key enzyme involved in serine catabolism, little is known about the functions of posttranslational modification in regulating SHMT2 in lung cancer." (PMID 38460155, 2024). "To determine the role of SHMT2 in lung cancer, we first investigated its clinical significance in LUAD." (PMID 38577602, 2024). "Animal studies examining the effects of dysregulated SHMT2 and miR-383-5p expression on the growth and metastasis of lung cancer must be conducted in the future to verify this possibility." (PMID 38577602, 2024). "Overexpression of Gm15290 can promote the proliferation of lung cancer by upregulating SHMT2 expression." (PMID 37127605, 2023). "In lung cancer, SHMT1 and SHMT2 are both highly associated with the infiltration of different types of immune cells, and are potential prognostic biomarkers." (PMID 37147729, 2023). "In lung cancer, SHMT2 is also a highly expressed oncogene, and its expression is highly related to tumor-infiltrating lymphoytes and shorter OS." (PMID 36699468, 2022). "SHMT2 expression is up-regulated downstream of oncogenic transcription factors including NRF2 in lung cancer and MYC in breast cancer." (PMID 32903271, 2020). "Here, we characterized the binding of SHMT1 to the 5′UTR of its mRNA and to three 5′UTRs of SHMT2 isoforms differently expressed in lung cancer, chosen on the basis of their relative abundance in RNA-sequencing data." (PMID 30809670, 2019). "On the other hand, we recently demonstrated the crucial role of SHMT1 for the survival of lung cancer cells; albeit being overexpressed also in these cells, SHMT2 appears to play a minor role." (PMID 26717037, 2016). "Consequently, SHMT1 and SHMT2 coordinate the folate cycle and contribute to cellular proliferation and metabolic demands in specific contexts such as lung cancer." (PMID 40738465, 2025). "This functional distinction between SHMT1 and SHMT2 suggests that targeting both enzymes could disrupt the metabolic reprogramming driving lung cancer progression." (PMID 40738465, 2025). "We noted a significant association of SSP genes as well as SHMT2 and MTHFD2 with the expression of the asparagine synthase (ASNS), an activating transcription factor 4 (ATF4) regulated marker for amino acid and glucose deprivation in both lung cancer subtypes." (PMID 38515202, 2024). "In this study, we analyzed the relationship between SHMT2, cyclinD1, and Bcl-2 in lung cancer." (PMID 38577602, 2024). "Thus, we concluded that decreased expression of miR-383-5p in lung cancer cells is responsible for the upregulation of SHMT2 and lung cancer development." (PMID 38577602, 2024).